IPO8 (importin 8)
Description:
Involved in nuclear protein import, either by acting as autonomous nuclear transport receptor or as an adapter-like protein in association with the importin-beta subunit KPNB1. Acting autonomously, may serve as receptor for nuclear localization signals (NLS) and promote translocation of import substrates through the nuclear pore complex (NPC) by an energy requiring, Ran-dependent mechanism. At the nucleoplasmic side of the NPC, Ran binds to importin, the importin/substrate complex dissociates and importin is re-exported from the nucleus to the cytoplasm where GTP hydrolysis releases Ran. The directionality of nuclear import is thought to be conferred by an asymmetric distribution of the GTP- and GDP-bound forms of Ran between the cytoplasm and nucleus. In vitro mediates the nuclear import of the signal recognition particle protein SRP19. May also be involved in cytoplasm-to-nucleus shuttling of a broad spectrum of other cargos, including Argonaute-microRNAs complexes, the JUN protein, RELA/NF-kappa-B p65 subunit, the translation initiation factor EIF4E and a set of receptor-activated mothers against decapentaplegic homolog (SMAD) transcription factors that play a critical role downstream of the large family of transforming growth factor beta and bone morphogenetic protein (BMP) cytokines (Probable).
Synonyms: Imp8; RanBP8; VISS
Tractability: PROTAC: ubiquitination databases record sites on it; its protein half-life has been measured.
Gene: Protein-coding gene on chromosome 12 (30,628,981 to 30,695,883, reverse strand). Ensembl gene ENSG00000133704.
Subcellular location: Cytoplasm; Nucleus
Subcellular location (Human Protein Atlas): Nucleoplasm; End piece; Vesicles
Pathways (Reactome):
Gene expression (Transcription): Transcriptional regulation by small RNAs
Gene Ontology:
Molecular function: protein binding; nuclear import signal receptor activity; small GTPase binding
Biological process: signal transduction; import into nucleus; intracellular protein transport
Cellular component: cytosol; nuclear envelope; nucleoplasm; cytoplasm; nucleus
Genetic constraint (gnomAD): Loss-of-function variants: 28 observed, 66.78 expected, observed/expected ratio (o/e) 0.42, 90% interval 0.31 to 0.57. The upper end of that interval is the gene's LOEUF score, 0.57, which puts it in group 2 of 6, group 1 being the genes least tolerant of losing a copy. Missense variants: 584 observed, 754.76 expected, observed/expected ratio (o/e) 0.77, 90% interval 0.72 to 0.83. Synonymous variants: 258 observed, 264.47 expected, observed/expected ratio (o/e) 0.98, 90% interval 0.88 to 1.08.
Homologues: Orthologues: chimpanzee IPO8 (99% identical), macaque IPO8 (99% identical), dog IPO8 (98% identical), pig IPO8 (97% identical), guinea pig IPO8 (94% identical), mouse Ipo8 (90% identical), rat Ipo8 (89% identical), tropical clawed frog ipo8 (77% identical), zebrafish ipo8 (70% identical), rabbit IPO8 (59% identical). Paralogues in human: IPO7 (64% identical), CSE1L (21% identical), IPO9 (16% identical), IPO11 (15% identical).
Diseases named in the same sentence as IPO8 in open-access papers:
IPO8 is named in the same sentence as 39 diseases in open-access papers, as found by Europe PMC text mining. Sharing a sentence is not in itself a finding about the gene and the disease. The quoted sentences say what the papers report.
non-small cell lung carcinoma (3 papers, 2017 to 2023). A group of at least three distinct histological types of lung cancer, including non-small cell squamous cell carcinoma, adenocarcinoma, and large cell carcinoma. "Paired and single cell line analyses under these experimental conditions identified TATA-Box Binding Protein (TBP) and Importin 8 (IPO8) to be stable in non-small cell lung cancer." (PMID 28262749, 2017). "Previously, IPO8 was found to be suitable for data normalization in endometrial and ovarian carcinomas, colon adenocarcinoma cell lines, non-small cell lung cancer, and other tissues and diseases: brain edema, heart cavities, T cells, and neutrophils." (PMID 30881377, 2019).
osteoarthritis (3 papers, 2019 to 2023). A noninflammatory degenerative joint disease occurring chiefly in older persons, characterized by degeneration of the articular cartilage, hypertrophy of bone at the margins and changes in the synovial membrane. "The importin 8 (IPO8), cancer susceptibility candidate 3 (CASC3), and TBP were recommended as RGs for studies on osteoarthritis patient-derived BM-MSCs." (PMID 31240211, 2019). "ABHD14A may be involved in the development of granule neurons, while IPO8 is involved in a common bone marrow mesenchymal stem cell degenerative joint disease." (PMID 31756171, 2019).
celiac disease (2 papers, 2016 to 2022). An autoimmune genetic disorder with an unknown pattern of inheritance that primarily affects the digestive tract. "The Delta-Delta CT (ΔΔCT) relative quantification method was used to estimate mRNA levels of target genes relative to a reference gene (IPO8) in the small intestinal biopsies from patients with celiac disease and compared with controls." (PMID 27483138, 2016).
colon cancer (2 papers, 2010 to 2013). "IPO8 is a Ran-binding protein mediating nuclear import and has been already reported stably expressed in lung tissues, gliomas, and colon cancer." (PMID 24001041, 2013). "Two pairs of genes, HPRT1/PPIA and IPO8/PPIA, were identified to be suitable to normalize gene expression data in metastatic and non-metastatic colon cancer patients, according to geNorm and NormFinder respectively." (PMID 21059236, 2010). "We identified two pairs of genes, HPRT1/PPIA and IPO8/PPIA, which may be suitable to normalize gene expression data in studies conducted in metastatic and non-metastatic colon cancer patients." (PMID 21059236, 2010).
endometrial cancer (2 papers, 2017 to 2020). Primary or metastatic malignant neoplasm involving the endometrium (mucous membrane that lines the endometrial cavity). "PSMC4, PUM1 and IPO8 were identified as the best reference genes combination for type 1 endometrial cancer (grades 1, 2 and 3), whereas for type 2 endometrial cancer (serous and carcinosarcoma), UBC, MRPL19, PGK1 and PPIA were the best reference genes combination." (PMID 32439920, 2020).
head and neck cancer (2 papers, 2017 to 2023). A primary or metastatic malignant neoplasm affecting the head and neck. "Data analysis and ranking of the top 5 HKGs using geNorm and Normfinder identified UBC, TBP, IPO8, TFRC, GAPDH in head and neck cancer; TBP, IPO8, GUSB, UBC in lung and TBP, IPO8, TFRC, GUSB, HMBS in pancreas to be stable." (PMID 28262749, 2017).
breast carcinoma (1 paper, 2025). "We transfected T47D breast cancer cells which express importin 8 at high levels (MDA-MB-231 breast cancer cells and DU-145 prostate cancer cells had lower expression), and observed EGFP cytoplasmic to nuclear presence by confocal microscopy." (PMID 40141456, 2025).
Cluster headache (1 paper, 2019). A type of headache characterized by repeated attacks of unilateral pain lasting 15 to 180 minutes and associated with local autonomic signs. "Also, we determined that TBP, IPO8 and PDHB were suitable reference genes in cluster headache fibroblasts." (PMID 31366133, 2019).
deafness (1 paper, 2014). An inherited or acquired condition characterized by the complete loss of the ability to hear from one or both ears. "Of them, 9 deafness genes expressed more in the apical turn (Pou4f3, Slc17a8, Tmc1, Crym, Otof, Ush1c, Pcdh15, Slc26a5, and Lhfpl5) and six were internal controls (Gapdh, Actb, Rps17, Rpl30, Atp6, and Ipo8)." (PMID 24676347, 2014).
developmental delay (1 paper, 2025). "Similarly, biallelic loss-of-function variants in IPO8 underlie a syndromic form of thoracic aortic aneurysm characterized by motor developmental delay, connective-tissue manifestations, and craniofacial dysmorphism (e.g., frontal bossing, hypertelorism, retrognathia, and ptosis)." (PMID 41465473, 2025).
Heat Stroke (1 paper, 2017). A condition caused by the failure of body to dissipate heat in an excessively hot environment or during PHYSICAL EXERTION in a hot environment. "When those four validated reference genes, SDHA, POLR2A, IPO8 and HMBS, were used for normalization, increased cerebral expressions of AQP4, CLDN5, OCLN, ZO1 and MMP9 were detected in heat stroke group." (PMID 28490769, 2017).
lung carcinoma (1 paper, 2008). "In view of all these results we conclude that IPO8 is the most robust reference gene for lung cancer studies." (PMID 19014639, 2008). "We thus propose IPO8 as a novel reference gene for lung cancer samples." (PMID 19014639, 2008).
malignant ovarian tumours (1 paper, 2013). "In conclusion, thorough statistical evaluation of our 13 candidate RGs identified IPO8 followed by RPL4 as the most suitable for the normalization of gene expression data in benign, borderline, and malignant ovarian tumours." (PMID 24001041, 2013). "We found IPO8 and RPL4 to be suitable reference genes for normalization of target gene expression in benign, borderline, and malignant ovarian tumours." (PMID 24001041, 2013).
meningioma (1 paper, 2011). A generally slow growing tumor attached to the dura mater. "Considering the results of the normalization of VEGFA against every single reference genes with significantly altered results for CASC3 and IPO8, NormFinder displays a more accurate ranking for meningiomas and their control tissue." (PMID 21806841, 2011). "Most reference genes maintained the ratio between brain, dura and meningioma except IPO8 and CASC3." (PMID 21806841, 2011). "TOST procedure showed statistical equivalence between normal tissue and meningiomas (± δ = ± 1.5) for three reference genes: CASC3 (+0.87), IPO8 (+0.57) and POP4 (+1.36)." (PMID 21806841, 2011). "Eight highest ranked reference genes (CASC3, EIF2B1, IPO8, MRPL19, PGK1, POP4, PPIA, and RPL37A) plus GAPDH and ACTB were then analyzed in 35 meningiomas, arachnoidea, dura mater and normal brain." (PMID 21806841, 2011). "Those three genes were not normally distributed in meningiomas (CASC3 (P-value = 0.002), IPO8 (P-value < 0.0001) and POP4 (P-value = 0.0005)." (PMID 21806841, 2011).
myxoid liposarcoma (1 paper, 2015). A liposarcoma characterized by the presence of round non-lipogenic primitive mesenchymal cells and small signet ring lipoblasts within a myxoid stoma with a branching vascular pattern. "We could identify B2M and IPO8 as suitable reference genes for myxoid liposarcoma and fat control samples in cryo-conserved as well as in formalin-fixed tissue." (PMID 26036639, 2015).
retinal degeneration (1 paper, 2017). Degeneration of the retina. "They include genes involved in nuclear trafficking and gene silencing (IPO8), fast axonal guidance and synaptic specificity (PCDH12), transduction of nerve signals (NRSN1), retinal degeneration (LMO7), synaptic glutamate release (SH3GL2), and broader nervous system development and function." (PMID 29064472, 2017).
cancer (11 papers, 2008 to 2025). A tumor composed of atypical neoplastic, often pleomorphic cells that invade other tissues. "Indeed, the importin 8-cargo interface could be an appealing target for small molecule- or peptide-based inhibitors in diseases in which importin 8 and its cargo proteins are implicated, including cancer and developmental disorders." (PMID 40141456, 2025). "In conclusion, we propose the use of IPO8, PUM1, HNRNPL, SNW1 and CNOT4 as reference genes in studies comparing gene expression between different cancer and/or normal cell lines." (PMID 34593877, 2021). "IPO8, PUM1 and HNRNPL were among the three most stable genes for our set of cancer cell lines and also for all cell lines investigated." (PMID 34593877, 2021). "The cross-tissue analysis of 12 cancer types revealed that the most stably expressed genes were: PUM1 (SExp = 70), IPO8 (SExp = 61), UBC (SExp = 60), ACTB (SExp = 55), and RPN1 (SExp = 54)." (PMID 30881377, 2019). "In contrast, IPO8, PUM1 and—in case of cancer cell lines—HNRNPL showed the lowest variation." (PMID 34593877, 2021). "Interestingly, IPO8 has never been proposed as a potential reference gene in cancer research." (PMID 19014639, 2008). "Interestingly, we observed that GAPDH, GUSB, IPO8, RPL13, RPL32, and UBC genes, as well as RPLP0 + TBP, RPL13 + RPL32, RPL13 + RPLP0, and ACTB + TBP RG pairs, were the only assays whose expression did not depend (P > 0.05) on cancer progression." (PMID 25225161, 2014).
tumor (5 papers, 2011 to 2023). "Filtering yielded 46 likely somatic mutations in the tumor, of which 7 (affecting EIF4A1, EPHA3, FAF1, IPO8, KIAA1377, LIMCH1, and NIPBL) were confirmed in the RNASeq results." (PMID 25861239, 2015). "Expression of IPO8, RPL4, TBP, RPLPO, and ACTB had the least variation in expression across the tumour samples according to GeNorm, NormFinder, and BestKeeper." (PMID 24001041, 2013). "Normalization with IPO8 or CASC3 showed significantly increased ratio for brain to dura and brain to tumour." (PMID 21806841, 2011).
connective tissue disorder (3 papers, 2021 to 2025). A disease involving the connective tissue. "Biallelic loss-of-function variants in IPO8 impair this process, resulting in a syndromic connective tissue disorder (VISS syndrome) with cardiovascular, skeletal, and immune abnormalities." (PMID 40981152, 2025). "Not only do zebrafish lacking the gene annotated to this CpG display skeletal and cardiovascular defects, but human loss of function mutations in IPO8 underlie a connective tissue disorder characterized by immune dysfunction as well as skeletal and cardiovascular anomalies." (PMID 39411517, 2024). "Loss-of-function variants in IPO8 impair SMAD translocation, resulting in a syndromic connective tissue disorder characterized by aortic aneurysms, skeletal anomalies, and immune dysregulation." (PMID 40981152, 2025).
infection (2 papers, 2023 to 2025). The state of being infected such as from the introduction of a foreign agent such as serum, vaccine, antigenic substance or organism. "We found several reference genes were differentially expressed in infection control mice (i.e., IPO8, PGK1 and ALAS1) in response to sporozoite challenge." (PMID 38030676, 2023).
bacterial infection (1 paper, 2018). "Our analysis revealed downregulation of miRNA-150 during bacterial infection may exert broad effects on metabolism (SLCA2A3/GLUT3), cytokine regulation (SOCS1), and cell signaling pathways (MAPK13, IPO8, ACVR1B, RNF146) consistent with the host response to bacterial infection." (PMID 30619110, 2018).
IPO8 also shares sentences with these, for which no sentence is quoted: colon adenocarcinoma (2 papers); pancreatic cancer (2); urinary tract infection (2); benign tumours (1); brain edema (1); carcinosarcoma (1); chronic lymphocytic leukemia (1); congenital heart defects (1); glioma (1); immune dysfunction (1); Infertility (1); leukemia (1); ovarian carcinoma (1); ovarian tumours (1); prostate carcinoma (1); ptosis (1); thoracic aortic aneurysm (1); viral infection (1).